DNMT1 (DNA methyltransferase 1)
Diseases named in the same sentence as DNMT1 in open-access papers (continued):
Sharing a sentence is not in itself a finding about the gene and the disease.
cancer (continued). "The expression level of DNMT1 increased obviously in non-differentiative cancer cells, and patients with DNMT1 positive expression had poor overall survival and relapse-free survival rates." (PMID 35838271, 2022). "DNMT1 inhibition and NNMT activation render OXPHOS‐sensitive cancer cells resistant in vitro; we thus further examined the effects of S‐Gboxin and Berberine on tumor xenografts by NCI‐H82 cancer cells with NNMT overexpression and DNMT1 knockdown (NCI‐H82‐OE‐NNMT/sh‐DNMT1)." (PMID 36382559, 2022). "As an example, trimethylation at H3K27 represses the production of CXCL9 and CXCL10 in ovarian cancer, establishing an immune-suppressive TME, while DNMT1 is responsible for the diminution of CXCL12 in osteosarcomas, resulting in reduced CTL recruitment at the cancer site." (PMID 35267528, 2022). "The positive pan-cancer correlations with m1A RNA methylation regulatory proteins YTHDF2 and ALKBH1, m5C methylation regulatory proteins DNMT1, DNMT3B, and ALYREF, and m6C RNA methylation regulatory proteins HNRNPC, HNRNPA2B1, and ELAVL1 were particularly significant." (PMID 36090896, 2022). "To check whether DNA methylation governed by DNMTs plays a role in the regulation of OXPHOS dependency for cancer cells, we examined cancer cell sensitivity to OXPHOS inhibition after manipulating the expressions of DNMT1 or NNMT or both." (PMID 36382559, 2022). "In particular, RMST was characterized as a positive regulator for DNMT3 but not DNMT1 by increasing DNMT3 mRNA stability in cancer." (PMID 36911851, 2022). "Since DNMT1 is responsible for the resistance of cancer cells to PARP inhibitors, we investigated whether FBP1 regulates the sensitivity to PARP inhibitors via DNMT1." (PMID 34854226, 2022). "To investigate the function of DNMT1 in HBV-GN, we collected renal biopsy samples from 15 HBV-GN patients, 15 HBV-antigen-negative PGN patients, 20 HBV-antigen-positive PGN patients, and 15 matched non-carcinoma samples." (PMID 35765066, 2022). "However, in cancer cells, DNMT3A and DNMT3B enzymes synergistically enhance the DNMT1 activity and shift its activity towards de novo DNA methylation." (PMID 33498667, 2021). "Additionally, they observed that ATRA and decitabine inhibited DNMT1, activated miR-34a via promoter hypomethylation, down-regulated its MYCN target, and therefore exhibited a synergistic anti-cancer action." (PMID 34835969, 2021). "The study shows that EZH2 dependent protein stability of LSD1, HDAC1, DNMT1, β-catenin, or SMAD2/4, via recruitment of deubiquitinase USP7, is key in suppressing neuronal genes and sustaining the expression of Wnt and TGFβ target genes in cancer cells." (PMID 34552611, 2021). "Collectively, the DNMT3A, DNMT3B, DNMT1, and ALYREF might function as poor prognosis predictors in cancer progression." (PMID 34325709, 2021). "Furthermore, dual inhibitors of DNMT1 and HDAC8 were introduced as novel potential candidates for epigenetic‐based cancer therapeutics for the first time in a recent study." (PMID 33314500, 2021). "LincRNA-mediated DNMT1 mis-localization has not been previously reported and has significant implications to DNA methylation regulation, as well as cancer and RNA biology." (PMID 33851096, 2021). "Thus, understanding the role of the UHRF1/DNMT1/HDAC1/G9a complex in reading the epigenetic marks (DNA methylation and histone marks) in cancer will allow the development of a new generation of multitarget epidrugs." (PMID 33922029, 2021). "DNMT1, a member of the DNMT family, was not only required for the maintenance of normal methylation in the developing mouse embryo 5, but also contributed to aberrant CpG island methylation in cancer cells." (PMID 33859766, 2021).
cancer (continued). "The depletion of HAUSP in several cancer cell lines resulted in a significant decrease in DNMT1 expression at the protein level, but not at the mRNA level." (PMID 35052383, 2021). "Because of the well-known role of DNMT1 in the inhibition of the expression of tumor suppressor genes, we determined if DNMT1 inhibitors could be utilized to re-express HEXIM1 in cancer cells." (PMID 33273553, 2020). "We observed that DNA methyltransferase genes such as DNMT1, DNMT3A, and DNMT3B were overrepresented in all cancer groups, with a significant difference between the SH and SL samples in both ADCs and SCCs, which prompted us to explore the genome for the methylation states." (PMID 33343623, 2020). "In cases when miRNAs capable of suppressing DNMT1, DNMT3A, DNMT3B and EZH2 are decreased, it could lead to abnormal DNA methylation patterns to silence specific gene targets, resulting in cancer." (PMID 33291485, 2020). "DNMT3a has been reported to be downregulated in some cancers, but DNMT1 is not known to be involved in the deregulated expression of genes." (PMID 32328088, 2020). "Interestingly, BRAP expression was strongly correlated with DNMT1, DNMT2, DNMT3A, and DNMT3B expression in human pan-cancer, and UCS, TGCT, and SARC were exceptions." (PMID 33240929, 2020). "As observed in cancer cells, TALE treatment also caused a decreased expression of Ezh2, Lsd1, Dnmt1, β-catenin, and Smad proteins in NPCs, but not a decreased Hdac1." (PMID 31130994, 2019). "Interestingly, our previously studies demonstrated that a major part of cancer promoting genes, including the genes for EZH2, LSD1, HDAC1/3, DNMT1, SMAD2/4, or β-catenin, are specifically expressed in embryonic neural cells." (PMID 31130994, 2019). "Although URHF1 mediates cross-talk between DNA methylation and histone acetylation through interaction with DNMT1 and HDAC1, HDACs may nonetheless be recruited to the silenced genes in the UHRF1-depleted cancer cells." (PMID 31064417, 2019). "Moreover, reduced EZH2 led to significantly reduced binding of LSD1, HDAC1, and DNMT1 to promoter regions of CDH1, CDKN1A, NEUROD1, and TUBB3, in agreement with increased transcription of these genes in cancer cells after EZH2 knockdown." (PMID 31130994, 2019). "Furthermore, we provide evidence for widespread co-expression of UHRF1 and DNMT1 and activated MEK/ERK pathway as a driving force for frequent UHRF1/DNMT1 overexpression in cancers." (PMID 30696879, 2019). "But unlike the case in mESCs, 2i regulates UHRF1/DNMT1 expression in cancer cells primarily at the level of transcription." (PMID 30696879, 2019). "Thus, DNMT1 methylation by SETD7 can be addressed as an interesting process to be explored in the development of new therapeutic strategies, particularly for cancer treatment." (PMID 30013796, 2018). "In this study, we observed that USP24 increased DNMT1 degradation in cancer cells, but not in M2 macrophages, leading to decreased DNA methylation." (PMID 30266897, 2018). "Blattler and colleagues also found that relatively few genes were dysregulated in DNMT1/3B double KO HCT116 cells, but some cancer/testis genes (the related GAGE genes) were upregulated, along with Krüppel-associated box genes, while chaperonins figured prominently among down-regulated genes." (PMID 29598829, 2018). "Functional studies also revealed that miR-148b-3p could act as a tumor suppressor via directly targeting distinct oncogenes such as DNMT3b, CCK2R, DNMT1, CEA and AMPKα1 in these cancers." (PMID 29661252, 2018). "In cancer tissues, DNMT3B is expressed more frequently compared to DNMT1 and DNMT3A." (PMID 29796115, 2018).
cancer (continued). "The DNA methylation enzyme DNA methyltransferase 1 (DNMT1) is the prototypical DNA methyltransferase and is widely assumed to be responsible for most of the methylation of the human genome, including the abnormal methylation found in cancers." (PMID 29581862, 2018). "In 12 studies with 781 cancers and 890 controls, we analyzed the DNMT1 different expression between GC and non-cancerous mucosa." (PMID 29221215, 2017). "Targeting both EBV and DNMT1, which are predominantly expressed in the NPC early stage, may be a good strategy in the EBV-positive cancer’s prevention and therapy." (PMID 29872698, 2017). "While the alteration of miR-148a expression has been used to modulate DNMT1 in many cancers, to our knowledge, it has not been utilized in donor cells." (PMID 28665977, 2017). "mRNA expression of DNMT1, DNMT3A, DNMT3B, and six different isoforms of DNMT3B were examined by real-time PCR, with only DNMT3B4 exhibiting significantly different expression levels between cancer tissues and adjacent normal tissues." (PMID 28160561, 2017). "Intriguingly and in contrast to what is observed in ES cells, KDM1A depletion in cancer cells was found not to trigger any reduction in the DNMT1 or DNMT3B protein level or any change in DNA methylation." (PMID 27449289, 2016). "Together, our findings propose a mechanistic link between KDM1A and DNA methyltransferases in cancer cells and suggest that the KDM1A/DNMT1 interaction may play a role during replication." (PMID 27449289, 2016). "Note that we could not directly evaluate the scope of DNA hypomethylation induced by overexpressed UHRF1 in cancer cells, because UHRF1 is also required for DNA maintenance methylation by DNMT1 and knockdown of UHRF1 compromises DNA methylation by DNMT1." (PMID 27462454, 2016). "Our preliminary study also showed upregulation of DNMT1 expression in HPV-positive cancers and keratinocytes (data not shown)." (PMID 27143385, 2016). "We next examined whether KDM1A knockdown might affect levels of DNMT1 and/or DNMT3B transcripts in cancer cells." (PMID 27449289, 2016). "Having observed that DNMT1 and KDM1A co-localize at replication foci in NIH3T3 cells, we wondered whether they interact directly in cancer cells." (PMID 27449289, 2016). "We provide evidence that in cancer cells, KDM1A interacts with both DNMT1 and DNMT3B." (PMID 27449289, 2016). "By targeting DNMT1, RhoA/Cdc42, and E2F6, miR-185 has been shown to induce cell cycle arrest and apoptosis, in addition to inhibiting proliferation and invasion in cancer cell lines and xenograft mouse models of various cancers." (PMID 26930719, 2016). "In this context, recent studies in human carcinoma cells have shown that MUC1-C drives transcription of DNMT1 and DNMT3b, but not DNMT3a." (PMID 27259275, 2016). "In positive cases for methylation of RASSF1A, the DNMT1 protein had been detected in 41 out of 45 (91%), while in non-methylated cancer cases, 20 out of 55(36.3%), and the difference is significant (P < 0.05)." (PMID 25886188, 2015). "However, in cancer cells treated with SFN, often a reduction of DNMT1 activity is observed, as documented in a study with human colon Caco-2 cells." (PMID 26703571, 2015). "Grifolin may represent a promising therapeutic lead compound for intervention of cancer metastasis, and it may also be useful as an ERK1/2 kinase inhibitor as well as an epigenetic agent to further our understanding of DNMT1 function." (PMID 26516701, 2015). "And furthermore, we also found that in the positive cases for methylation of RASSF1A, the DNMT1 protein had overexpressed in non-methylated cancer cases with significant difference (41 DNMT1 positive cases in 45 RASSF1A positive cases)." (PMID 25886188, 2015). "We chose HEK 293 T cells as a non-cancer cell type that is widely available, allowing replication of our studies and an insight into effects of DNMT1 inhibitors in cells that have not undergone malignant transformation." (PMID 25806086, 2015).
cancer (continued). "In the CpG-island-methylated esophageal squamous carcinoma cases, the DNMT1 protein has been detected in 41 out of 45 (91%), while in non-methylated cancer cases, 20 out of 55(36.3%), and the difference is significant (P < 0.05)." (PMID 25886188, 2015). "The data revealed that only 45 (36%) cancer specimen had higher DNMT1 compared to adjacent non-malignant epithelial tissues." (PMID 24625449, 2014). "Expression of LMP1 alone in human cancer B-cells was sufficient to efficiently inhibit DOK1 transcription by promoting the formation of a transcriptional repressor complex containing E2F1, pRB, and the DNA methyl-transferase DNMT1." (PMID 24809689, 2014). "Given that the aberration of both NCL and DNMTs frequently occurs in cancers, we hypothesized that NCL may accelerate leukemogenesis via DNMT1-dependent DNA hypermethylation that is driven by NCL-NFκB cascade." (PMID 25015109, 2014). "The exact mechanisms of DNMT upregulation remain unclear, but it is suggested that aberrant DNMT activity, especially with regard to DNMT1, is due to a rapid proliferation of cancer cells because DNMT1 binds to proliferating cell nuclear antigen (PCNA)." (PMID 25197641, 2014). "The link between the DNMT isozyme DNMT1 and cancer initiation and progression is well established." (PMID 24236046, 2013). "Considering its DNMT1 suppressing effect, THL might have potential as a candidate agent for epigenetic cancer therapy." (PMID 19897545, 2011). "Alterations in the transcription of DNMT1 and DNMT3B are likely key contributors to the global DNA hypomethylation and region‐specific hypermethylation observed in aging cells, while the expression of all DNMTs tends to be significantly upregulated in cancer cells (Casillas Jr." (PMID 41482638, 2026). "While these SNPs do not appear to influence DNMT1 protein expression directly, they may affect the protein’s function or structure, contributing to cancer development." (PMID 41602389, 2026). "Cigarette smoking affects the expression DNMT1, which may be involved in cancer pathogenesis through de novo methylation of tumor suppressor genes." (PMID 40003580, 2025). "Interestingly, analyzing the three epigenetic modifiers together, we found that the simultaneous overexpression (3 +) of at least two of the three proteins (DNMT1, G9a, and UHRF1) in cancer cells resulted in a significant shorter DFS and OS when all PDAC patients were analyzed together." (PMID 39810240, 2025). "In various malignant tumors, the CpG islands enriched in the 5′ promoter region of the RASSF4 gene often undergo abnormal methylation modifications, a process primarily mediated by DNA methyltransferases 1 (DNMT1) and DNMT3A/B, leading to transcriptional silencing of the gene." (PMID 41007433, 2025). "We analyzed the correlation between DNMT1 expression level and cellular sensitivity to all drugs and drug combinations (n = 545) in the Cancer Target Discovery and Development (CTD^2) database across a large panel of human cancer cell lines (798 cell lines in total)." (PMID 39930152, 2025). "Also, excessive expression of miR‐148a in cancer cell lines led to a decline in DNMT1 expression and hindered cell proliferation without any noticeable alteration in apoptosis rates." (PMID 40387409, 2025). "In addition, silencing DNMT1, which leads to the upregulation of CDH1, also known as the DNMT1/CDH1 loop, in the presence of excessive ectopic expression of miR‐152 effectively inhibits the migratory capability of cancer cells." (PMID 40387409, 2025). "Interestingly, DNMT1 is a target of miR-152, and its levels are inversely related to miR-152 in many cancers, suggesting a negative feedback loop between them." (PMID 39606232, 2024). "The unmet therapeutic needs in cancer treatment, as well as the scarce amount of DNMT1 inhibitors on the market, prompted us to further investigate the development of novel non-nucleotide DNMT1 inhibitors." (PMID 39595939, 2024).
cancer (continued). "In addition, we analyzed the correlation between PGAM1 and methylation-related genes, and the results showed that PGAM1 had significant correlations with methyltransferases such as DNMT1, DNMT3A and DNMT3B as well as methylation modifications such as m1A, m5C and m6A across various cancers." (PMID 38434965, 2024). "While UHRF2 could not only interact with other Ub/UBL-related proteins that regulate Ub/UBL protein modification, it could also interact with PCNA, DNMT1, HDAC1, and TRDMT1, which participate in DNA replication, cell cycle progression, microRNAs in cancer, etc.." (PMID 38879525, 2024). "Therefore, we hypothesize that treatment with DNMT1 inhibitors may constitute an alternative to UHRF1 targeting and may be a potential therapeutic approach for treatment of KRAS-driven cancer." (PMID 37407562, 2023). "LINC00922 binds to DNMT1, DNMT3A, and DNMT3B and is enriched in the promoter region of the downstream tumor suppressor NKD2, thereby inhibiting its expression through methylation, which ultimately activates the Wnt signaling pathway and promotes cancer progression." (PMID 37901333, 2023). "Our results showed that DNMT1 expression was elevated from non-neoplastic to tumor tissue at the mRNA and protein levels and further increased with grade progression and in tumor relapses, and its phosphorylation levels were also increased in carcinomas." (PMID 37894317, 2023). "In cancer cells, aberrant poly(ribosyl)ation activity or its controlling PARG activity disrupts DNA methylation; in some cases, it may be hyper- or hypomethylation depending on the cues that affect the poly(ribosyl)ation of DNMT1." (PMID 35327610, 2022). "However, while high DNMT1 levels in fibroblasts correlated significantly with poorer disease-free survival (DFS) (P = 0.0295), DNMT1 expression level in cancer cells did not significantly correlate with patient DFS (P = 0.4033)." (PMID 35719957, 2022). "Similarly, a reduction in DNA methyltransferase 1 (DNMT1) may promote induction of EMT and the cancer stem cell (CSC) phenotype, which facilitates tumorigenesis in PCa cells." (PMID 34199763, 2021). "In addition, DNA methylation may play an important role in tumor progression, and PBK/TOPK expression was positively correlated with methyltransferase expression, including DNMT1, DNMT3A, and DNMT3B, in most cancers except CHOL." (PMID 34603451, 2021). "The non-nucleoside inhibitor RG108 (N-phthaloyl-l-tryptophan 1) and selective non-nucleoside DNMT1 inhibitors in the DC_05 series of compounds (DC_501 and DC_517) can also play an anti-cancer role by inducing DNA hypomethylation to restore the expression of TSGs." (PMID 32751889, 2020). "It would be important to analyze whether procainamide, a fairly stable non-nucleoside inhibitor of DNMT1, will prevent cancer from arising." (PMID 33312959, 2020). "Taken together, these data provide compelling evidence that 2i broadly inhibits UHRF1 and DNMT1 expression in cancer cells by inhibition of the MEK/ERK pathway, which is broadly required for elevated transcription of both UHRF1 and DNMT1 in various cancer cells." (PMID 30696879, 2019). "Thus, the regulation of DNA methylation homeostasis in cancers is likely complicated and influenced not only by the elevated expression of UHRF1/DNMT1 but also by other parameters such as the activity of UHRF1/DNMT1, expression and activity of de novo DNA methyltransferases and TET family proteins." (PMID 30696879, 2019). "Therefore, we deduced that Sp1 might recruit DNMT1 to promote DNA methylation in the PDSS2 promoter region, resulting in repressed expression of PDSS2 transcription in cancer cells." (PMID 31783675, 2019).